CRP (C-reactive protein)
Diseases named in the same sentence as CRP in open-access papers (continued):
Sharing a sentence is not in itself a finding about the gene and the disease.
diabetes (continued). "Participants with both higher hs-CRP (> 3.0 mg/L) and worse cognition were older, were less likely to take regular exercise, smoke, drink, and currently married (P for trend all< 0.05), and more likely to suffer with diabetes, stroke and cerebrovascular disease (P for trend all< 0.05)." (PMID 31832073, 2019). "One of observation from Medical University of Vienna, Austria evidenced that administration of gallic acid in the amount of daily consumption could reduce oxidative DNA damage, oxidized-LDL and C-reactive protein in plasma of patients with type 2 diabetes mellitus." (PMID 30591041, 2018). "The first acute-phase protein to be described, C-reactive protein (CRP), produced by the liver and the adipose tissue, is a sensitive marker of inflammation known to be increased in obesity and involved in the pathogenesis of coronary heart disease and diabetes mellitus." (PMID 29849863, 2018). "Moreover, we found that serum albumin concentration may differently affect patient survival according to age, status of diabetes, UF volume, serum creatinine level, total cholesterol level, ferritin level, and hs-CRP level." (PMID 29694445, 2018). "They reached the conclusion that associations between CRP and diabetes are likely to be noncausal." (PMID 30619477, 2018). "People with DM and periodontitis usually have elevated circulating proinflammatory mediators, like TNF-α, IL-6, CRP, and reactive oxygen species (ROS) that can interfere with diabetes metabolic control and may act synergistically in worsening cardiovascular complications in diabetes." (PMID 30356347, 2018). "Sarcopenia is associated with elevated levels of markers of inflammation such as CRP and interleukin (IL)-621, and the prevalence of sarcopenia is higher in patients with other disease such as chronic obstructive pulmonary disorder, hypertension, diabetes, and CVD22." (PMID 30065297, 2018). "Diabetes in this case becomes a confounding factor, in that it establishes a low-grade inflammatory state, characterized by elevated levels of acute phase reactants such as CRP, interleukin-6 (IL-6), secretory phospholipase A2 and tumor necrosis factor alpha (TNFα)." (PMID 29547660, 2018). "Patients in higher AAC group were significantly older and had higher incidences of diabetes mellitus (DM), HbA1c, fasting serum glucose, C-reactive protein (CRP), and lower serum creatinine and left ventricular ejection fraction (LVEF)." (PMID 30353094, 2018). "Hence, the clinical potential of targeting CRP in the prevention of diabetes remains uncertain." (PMID 28178951, 2017). "Our finding of a positive association between CRP and increased risk of undiagnosed diabetes but not incident diabetes suggests that CRP might not be a causal factor for diabetes, but is a marker of hyerglycaemia in the pathway." (PMID 28178951, 2017). "Post-hoc subgroup analyses from previous epidemiologic studies in the SHS demonstrated that associations between urine arsenic and incident CVD and CHD were stronger among participants with diabetes, and CRP was associated with incident CVD only in those without diabetes." (PMID 28771557, 2017). "Participants with partial or complete tooth loss were more likely to be older, female, and less educated, and have less alcohol consumption, slower walking speed, less physical activity, more often CVD, hypertension, diabetes, and dementia, and high CRP compared to participants without tooth loss." (PMID 27682433, 2017). "However, when stratified by baseline HbA1c levels, we found that CRP was only positively associated with T2D among those already with high HbA1c levels (undiagnosed diabetes), but not in those with low HbA1c levels (incident diabetes)." (PMID 28178951, 2017).
diabetes (continued). "A prospective study looking at Mg intake and incidence of diabetes, systemic inflammation, and insulin resistance in young American adults followed up for 20 years (n = 4497) showed a significant inverse relationship with Mg intake and hs-CRP, IL-6, fibrinogen, and HOMA-IR." (PMID 29093983, 2017). "Therefore, it is of scientific interest whether CRP could predict the onset of diabetes in Chinese population with relatively lower levels." (PMID 28178951, 2017). "In addition, soft drinks contain caramel colouring which are rich in AGEs promoting inflammatory mediators that might be important in the development of diabetes, such as C-reactive protein and TNF-α." (PMID 29362720, 2017). "Of these, 2470 were excluded because of missing values (missingness was not mutually exclusive) on socioeconomic indicators (N = 89), behavioural factors or inflammatory markers (N = 1028), unknown diabetes status (N = 10), prevalent diabetes at baseline (N = 800) or CRP levels ≥10 mg/l (N = 1626)." (PMID 27101929, 2016). "However, there is no apparent causality between serum CRP, IR, and diabetes, which suggests that CRP is more likely to be a downstream marker rather than an upstream effector that links inflammation to IR." (PMID 26136779, 2015). "This condition is characterized by overproduction of proinflammatory mediators, such as circulating levels of C-reactive protein (CRP), TNF-α, and IL-1β, as well as insulin resistance and dyslipidemia, all of which are risk factors for cardiovascular diseases, metabolic syndrome, and diabetes." (PMID 26490535, 2015). "Moreover, the negative findings of the studies regarding CRP related genes and diabetes risk do not preclude a causal role for the inflammatory process (of which CRP is an indicator) in development of diabetes." (PMID 25994228, 2015). "Furthermore, this investigation was limited to patients with diabetes, and therefore, an association between AGEs, RAGE, and CRP with other parameters in subjects without diabetes should also be assessed." (PMID 26578953, 2015). "Our findings are consistent with some studies that directly compared patients with diabetes with those without and found that associations between CRP and CVD were generally weaker and not significant in patients with type 2 diabetes compared with non-diabetic individuals." (PMID 25899452, 2015). "Also, sRAGE was significantly associated with age in the control group (B = −47.1, R2 = 0.081 and p = 0.033, controlling for MG-H1), in girls with diabetes (B = −61.6, R2 = 0.154 and p = 0.001, controlling for CRP) and in control girls (B = −99.1, R2 = 0.154 and p = 0.001, no confounding variables)." (PMID 26408307, 2015). "CRP levels are elevated in a large proportion of patients with at least one cardiovascular risk factor, without diabetes mellitus who are not receiving statin therapy, suggesting a higher level of cardiovascular risk than predicted according to conventional risk estimation systems." (PMID 24564178, 2014). "In conclusion, we have shown that a large proportion of patients aged over 50 years and with at least one traditional cardiovascular risk factor but no previous history of CVD, who do not have diabetes mellitus and who are not currently being treated with statins, have elevated levels of CRP." (PMID 24564178, 2014). "This study found a significant positive correlation between the serum CRP level, daily smoking quantity, and type 2 diabetes after adjusting for the potential confounders of age, gender, occupation, education, monthly income, family history of diabetes, alcohol consumption, and physical exercise." (PMID 25105149, 2014). "In a recent study conducted in a general community-dwelling Japanese population, elevated serum ANGPTL2 levels were positively associated with the development of type 2 diabetes mellitus independent of other risk factors including C-reactive protein (CRP) levels." (PMID 24478758, 2014).
diabetes (continued). "The potential mediators between life course SEP and CRP included clusters of health-risk behaviors (smoking, low leisure time physical activity, excessive alcohol consumption), and metabolic alterations (obesity, hypertension, low HDL, hypertriglyceridemia, and diabetes)." (PMID 25309988, 2014). "Accordingly, most of the complications of diabetes mellitus resulted from endothelial dysfunction and activation, which characterized by reduced NO production and inflammatory cytokines up-regulation and subsequently leaded to plasma levels of Hs-CRP increase and APN decrease." (PMID 25070472, 2014). "An increase of C-reactive protein is an independent predictor of type 2 diabetes in apparently healthy women, supporting the hypothesis that subclinical inflammation has a role in the pathogenesis of diabetes." (PMID 23940623, 2013). "Elevated serum C-reactive protein (CRP), homocysteine, and higher 24-hour urine free cortisol may provide another additional mechanism whereby depression increases the risk of chronic disease such as CHD and diabetes." (PMID 24199205, 2013). "In addition, circulating PA was associated with inflammatory marker CRP and the presence of diabetes, but not with markers of liver injury aminotransferases." (PMID 22701277, 2012). "However, this increase may be due to the higher prevalence of hypertension, diabetes, serum triglycerides, and glucose in this group, suggesting a pattern of metabolic syndrome that is known to increase CRP." (PMID 22701354, 2012). "The association between SDB and high CRP was present mainly in women and Mexican Americans, implying SDB has a residual, independent association with inflammation after controlling for lifestyle and metabolic risk factors like BMI, physical activity, depression, diabetes, and cholesterol." (PMID 22518315, 2012). "Neither CRP nor GGT was associated with the presence of diabetes defined by the HbA1c criterion." (PMID 21076541, 2010). "Although not statistically significant, individuals with diabetes showed a consistent negative association with CRP and almost all traffic indices in what could be a result of the anti-inflammatory effects of noninsulin medications." (PMID 20123638, 2010). "Studies suggest elevated CRP levels may predictive for cardiovascular disease and diabetes." (PMID 22505974, 2009). "Research in diseased populations, such as diabetes, arthritis, prolonged chronic illness, and clinical vitamin D deficiency (25(OH)D <27.5 nmol/L) have demonstrated negative associations between vitamin D status and CRP concentrations." (PMID 18652680, 2008). "A multivariable model including Charlson Comorbidity Index (CCI), CRP, PLR, and diabetes predicted Clavien-Dindo ≥ IIIA complications with excellent accuracy (AUC 0.870)." (PMID 41753314, 2026). "Furthermore, with the development of highly sensitive CRP measurement methods, its importance as a biomarker is gaining attention not only in acute inflammatory diseases but also in chronic inflammatory diseases such as cardiovascular disease, diabetes, cancer and neurological disorders." (PMID 42274591, 2026). "While established protein markers such as IL-6 and CRP reflect inflammation status, they lack exposure-specificity and are strongly influenced by chronic comorbidities, most notably diabetes mellitus (DM)." (PMID 41596268, 2026). "Haplotype CCCC correlated positively with CRP (r = 0.14, P = 0.006); TTTT was significantly negatively correlated with erythrocyte sedimentation rate, CRP, and the presence of diabetes (r = -0.18, -0.15, and -0.14; P < 0.001, 0.003, and 0.008, respectively)." (PMID 40685733, 2026). "Hypoechoic and necrotic malignant lesions, diabetes mellitus, tuberculosis, immunosuppression of the patient, the number of biopsies obtained, EUS-B FNBs, and pre-procedural increases in CRP seem to be related to increased infective complications rates." (PMID 39857029, 2025).
diabetes (continued). "The combined analysis of C-reactive protein, serum WBC count, and albumin test results, can provide an early identification basis for sepsis in patients with diabetes complicated with UTIs." (PMID 40510484, 2025). "These selected variables were age, sex, psoriasis duration, PASI score, hypertension, diabetes, LDL-C level, CRP, and history of biologic therapy." (PMID 41112228, 2025). "These associations remained consistent in the fully adjusted model (Model 3), which accounted for potential confounders such as age, sex, Kt/V, diabetes mellitus, BMI, GNRI, CVD, NT-proBNP, and CRP." (PMID 41464631, 2025). "Excluded participants were more likely to suffer from obesity, hypertension, diabetes and CKD, and had higher blood levels of TG, uric acid and C-reactive protein." (PMID 39950154, 2025). "The study found that CRP, MMP-2, MMP-14, TIMP-2, and IFN-γ contribute to the inflammatory processes driving periodontal damage in diabetes." (PMID 40075856, 2025). "No significant statistical differences were observed between the two groups in terms of gender, blood pressure, diabetes, coronary heart disease (CHD), WBC, neutrophils, lymphocytes, erythrocytes, HB, FBG, CRP, and LVEF levels (p > 0.05)." (PMID 40852601, 2025). "At λ = 0.033, seven variables were selected from the 20 initially analysed: age, limb dysfunction, diabetes, tube feeding, BMI, NIHSS score and C-reactive protein." (PMID 39979762, 2025). "Accounting for patients’ fundamental conditions—such as gender, age, hypertension, and diabetes, as well as other lipid-related indicators (TC, HDL, and LDL), liver function indicators (ALBI and APTT), and inflammatory markers (CRP), PSM was performed." (PMID 40756516, 2025). "The final model included age, gender, BMI, diabetes status, WBC count, CRP level, preoperative imaging, and postoperative antibiotic duration as covariates." (PMID 41477174, 2025). "The markers of inflammation involved in the bidirectional relationship between OSA and diabetes are tumor necrosis factor-α (TNF-α), interleukin-6 (IL-6), and C-reactive protein (CRP)." (PMID 41155523, 2025). "Hormonal and Inflammatory Markers: Elevated serum insulin, HbA1c, and C-reactive protein (CRP) levels were observed, indicating disrupted glucose metabolism and systemic inflammation, key contributors to diabetes and CVD." (PMID 41459237, 2025). "Periodontal pathogens in the bloodstream increase C-reactive protein (CRP) levels and other pro-inflammatory cytokines, contributing to chronic low-grade inflammation—a key feature of diabetes and other metabolic disorders." (PMID 40136728, 2025). "For the all-cause mortality model, selected variables included: age, LDH, PLT, K, hypertension, NMLAR, BUN, CRP, Cr, NLR, lgPLR, diabetes, arthritis, smoking status, and Na." (PMID 41488918, 2025). "By modulating inflammatory markers such as CRP, IL-6, and TNF-α, exercise can help alleviate both the physical and psychological burdens of diabetes." (PMID 40860530, 2025). "Compared to participants with normal handgrip strength, those with weak handgrip strength generally had lower BMI and WC; higher levels of CRP, HDL-C, and BUN; and were more likely to have diabetes and hypertension." (PMID 41181352, 2025). "Compared to the group with normal ABIs, the individuals with low ABIs had more of the following conditions: diabetes mellitus (DM, p = 0.030), urine protein-to-creatinine ratio (p = 0.031), serum C-reactive protein concentrations (p = 0.037), and serum endocan levels (p < 0.001)." (PMID 40282868, 2025). "Meanwhile, WHR, diabetes, LDL-C, and hs-CRP were more likely to be correlated with arteriosclerosis in females." (PMID 40026504, 2025). "These variables included sex, age, comorbidity with diabetes or hypertension, APACHE II score, S100A9, PCT, lactate, and CRP." (PMID 40478888, 2025).
diabetes (continued). "Comparative analysis revealed significant between-group differences (P < 0.05) in age, diabetes status, operative duration, blood transfusion, internal fixation use, postoperative NLR, and CRP/ALB ratio." (PMID 41019129, 2025). "There was not any multicollinearity of GFAP levels with age, hypertension, diabetes, baseline NIHSS score, DWI-ASPECTS 0–7, WMLs and hyper-sensitive C-reactive protein levels (all VIF < 10)." (PMID 40421099, 2025). "Diabetes, LDL-C, and hs-CRP were more likely to be correlated with arteriosclerosis in females than in males (odds ratio (OR): 2.32, 1.26, 1.08 vs. 1.83, 1.17, 1.02, respectively, p < 0.05)." (PMID 40026504, 2025). "Autoantibodies, CRP, TSH, markers of autoimmune anemia (e.g. DAT) and diabetes (hemoglobin A1c) and vitamin B12 levels were also similar between the two groups." (PMID 40977722, 2025). "Min = 0.05998), including sex, history of hemoptysis, smoking history, hemoptysis volume, diabetes, NOB, NOC, pleural thickening, PLT, CRP, duration of hospitalization, and sputum culture results." (PMID 40443510, 2025). "In a study done in Sri Lanka, diabetes mellitus, hypertension, or dyslipidaemia for 10 years, elevated CRP (C-reactive protein), and hyperhomocysteinemia were found to be independent risk factors for PVD." (PMID 40400795, 2025). "This meta-analysis highlights the significant potential of probiotics in improving inflammatory and oxidative stress markers like CRP, TNF-α, and MDA, while boosting antioxidant defenses such as GSH, TAC, and NO in patients with diabetes mellitus." (PMID 40123937, 2025). "Logistic regression identified CRP (OR: 6.21), PPBS (OR: 4.76), history of PCOS (OR: 3.66), and family history of diabetes (OR: 3.45) as independent predictors of GDM." (PMID 41200603, 2025). "Central cytokine linking CKD, diabetes, and CVD; ↑ IL-6 and CRP correlate with low eGFR; therapeutic target." (PMID 41154568, 2025). "The only notable differences were the lower prevalence of diabetes and a slightly higher TAPSE value among those with elevated CRP." (PMID 40894478, 2025). "For the CLRD-specific mortality model, the final covariates included: age, smoking status, NMLAR, diabetes, LDH, AST, ALT, WBC, PLT, Cr, BUN, K, CRP, NLR, lgPLR, and education level." (PMID 41488918, 2025). "Research into the relationship between the ratio of high-sensitivity C-reactive protein (hs-CRP) and high-density lipoprotein cholesterol (HDL-C) concerning type 2 diabetes mellitus (T2DM) is still scarce." (PMID 40123888, 2025). "Model 1 used sex, years since diabetes diagnosis, age, and BMI; Model 2 used albumin, HbA1c, PCA-derived inflammation score, CRP, and eGFR." (PMID 41226704, 2025). "In the CLRD-specific mortality model, the highest-ranking variables included inflammation-related markers (NMLAR, WBC, NLR, lgPLR, CRP), hepatic indices (AST, ALT, LDH), renal markers (Cr, BUN), electrolytes (K), and smoking and diabetes." (PMID 41488918, 2025). "Restricted cubic spline analysis revealed a nonlinear relationship between the TG level and hypertension after adjusting for sex, age, diabetes, alcohol consumption, smoking, stroke, AMI, and Cr, RBS, CRP, TC, HDL-C, LDL-C, and HbA1c levels (P = 0.024)." (PMID 41584291, 2025). "Of the 18 characteristics (i.e., age, gender, course of diabetes, Course of DF, WBC, CRP, Hb, PLT, Cr, UA, HDL-C, LDL-C, FIB, INR, HbA1c, wagner grade, LEAD, PN) were collected." (PMID 40604114, 2025). "Among these, a nomogram incorporating seven predictive factors—age, limb dysfunction, diabetes, tube feeding, BMI, NIHSS score and CRP—was established as a practical tool for early sarcopenia screening." (PMID 39979762, 2025). "The detailed comparison between MASLD and non-MASLD participants revealed significant differences in age, gender, BMI, smoking status, diabetes, ALT, AST, total cholesterol, and hs-CRP levels (P < .05)." (PMID 40938077, 2025).